KRAS (KRas proto-oncogene, GTPase)
Diseases named in the same sentence as KRAS in open-access papers (continued):
Sharing a sentence is not in itself a finding about the gene and the disease.
tumor (continued). "Knowledge of the rather low expression of mutated KRAS in the patient’s tumor might have allowed a combinatorial anti-EGFR treatment to potentially improve the outcome." (PMID 31805664, 2019). "Moreover, this study showed the same point mutation sequence in tumor and corresponding lymph node metastases giving the impression that the phenomenon of intratumor heterogeneity of KRAS mutation in NSCLCs is very rare." (PMID 30368666, 2019). "These KRAS mutations may dominate over the tumor-specific mutations, as demonstrated in our case series." (PMID 30611220, 2019). "Notably, an anergic/monoclonal anti-tumor TCR repertoire was observed in a patient with KRAS/STK11 co-mutations and an early relapse after PD-1 blockade." (PMID 30400822, 2018). "The most frequently mutated genes across all tumor types included KRAS (30 patients), PIK3CA (16 patients), BRAF (6 patients), EGFR (5 patients), NRAS (4 patients) and ERBB2 (3 patients) whereas CCND1, ERBB2, EGFR and MYC were the genes most frequently subjected to copy number gain." (PMID 29854313, 2018). "In addition to known activating NRAS mutations in 18% (11/63) of tumours, we identified an activating KRAS G12A mutation." (PMID 29559732, 2018). "The expansion of KRAS-activating mutations to generate large patch sizes lends itself to this outcome and demonstrates how powerful oncogenes may actively contribute to tumor development through a field cancerization effect." (PMID 29779891, 2018). "A KRAS codon 12 mutation (G12V) was detected in the tumor tissue." (PMID 30043132, 2018). "HRAS and KRAS mutations have been identified in up to 50% of human UPS tumours." (PMID 29731980, 2018). "Oncogene-induced senescence, epigenetic alterations, or kinase-inactive mutation may be associated with the tumor evolution of KRAS- or BRAF-mutated adenocarcinoma." (PMID 29690599, 2018). "This classification divides CRC into four subtypes: MSI immune with MSI, BRAF mutated, and CIMP positive tumours; canonical with WNT and MYC activation; metabolic with KRAS mutated tumours; and mesenchymal, characterized by stromal infiltration and TGF-β activation." (PMID 30188916, 2018). "Overall, in 26 cases ctDNA analysis revealed a KRAS mutation that was not previously found in tumour tissue (i.e., 22 patients previously classified as having KRAS wild-type tumours and 4 patients with KRAS mutant tumours who were found to have a different KRAS mutation in ctDNA)." (PMID 29362371, 2018). "In 10 patients, there was discordance between the results of KRAS mutation in LB and tumor tissue." (PMID 30705875, 2018). "This suggests gsp may contribute to chronic pancreatic disease but secondary mutations, such as KRAS activation, are necessary for transformation and tumor progression." (PMID 29544460, 2018). "Tumor response was also evaluated in the human colorectal cancer model HCT116, which harbors a G13D mutation in KRAS rendering the tumor less sensitive to cetuximab treatment, as it is equally important to demonstrate that imaging biomarkers are negative when a tumor is nonresponsive to therapy." (PMID 29794225, 2018). "Higher levels of PD-L1 expression in tumor samples may explain better outcomes of PD-1/PD-L1 inhibitor therapy in patients with KRAS mutation." (PMID 29484144, 2018). "Thus, this T cell therapy represents a potential tumor cell-specific recognition technique, uniquely targeting tumor cells expressing the KRAS G12D mutation and the HLA-C∗08:02 allele." (PMID 29725606, 2018). "In our study, the percentage of the four tumor subgroups, including dMMR/KRAS mutation, dMMR/KRAS wild-type, pMMR/KRAS mutation and pMMR/KRAS wild-type tumors was 6.78%, 8.4%, 35.88%, 48.94%, respectively, which is similar to the data reported by a study from Beijing, China." (PMID 29423347, 2018).
tumor (continued). "All the tumor areas sampled were analyzed for KRAS, BRAF, PIK3CA, and NRAS mutations." (PMID 29774112, 2018). "In summary, KRAS mutations alter NF-κΒ signaling in tumor cells." (PMID 29445180, 2018). "The median value of MctDNA for the number detected in patients with the WT was 1/7 of that in patients with the MT, suggesting that about 1/7 of tumor cells (14.7%) in patients with the WT might have the KRAS mutation." (PMID 29849949, 2018). "Gender, age, and tumor location distribution of cases used in KRAS and BRAF mutation analysis." (PMID 29879227, 2018). "Therefore, the landscape is becoming complex considering that KRAS mutations can concomitantly occur with two or more driver alterations in the same tumor." (PMID 29464099, 2018). "The KRAS mutation could finally also be detected in the primary tumor, when additional tumor samples were tested." (PMID 29774112, 2018). "The concordance between tumor tissue and ctDNA KRAS mutation was 81.25%." (PMID 29707525, 2018). "We explored the BRAF and KRAS mutations (codon 12, 13, 59, and 61) in tumor tissues." (PMID 30509319, 2018). "Activating RAS mutations (11 NRAS and 1 KRAS mutation) were identified in 12/63 (19%) tumours." (PMID 29559732, 2018). "Glucose deprivation in tumors was reported to induce KRAS mutations, suggesting insufficient oxygen or nutrients in the tumor induced by anti-VEGF antibody may be involved in this mechanism." (PMID 29849949, 2018). "An early mutation in KRAS has been implicated in the progression of pre-malignant pancreatic intra-epithelial neoplasia to invasive malignancy, and has also been demonstrated to play a vital role in tumour maintenance." (PMID 29382047, 2018). "Our data revealed mutations that were shared by both tumor tissues and blood, suggesting that tumor cells with acquired KRAS mutations may travel to the blood." (PMID 29849949, 2018). "Similar to EGFR, the KRAS status may also be discordant between primary and metastatic tissues and a KRAS mutation in a small subset of tumor cells may confer resistance to EGFR tyrosine kinase inhibitors (TKIs) therapy." (PMID 29868480, 2018). "They observed a higher rate of KRAS mutation in the tumor center compared with the front invasion, suggesting that tumor samples should be preferably taken from the tumor center, while no information was given if the profiling differed between both superficial and deep primary tumor sectors." (PMID 29774112, 2018). "In this case, the mutation was found in the CTC and wild-type KRAS was found in the primary tumor." (PMID 28468669, 2017). "In particular, the BRAF V600E mutation (rs113488022) in exon 15, which occurs in 8-10% of colorectal tumors and is mutually exclusive with KRAS mutations, was found to be associated with a more aggressive tumor phenotype, lymph node metastasis, and high microsatellite instability (MSI)." (PMID 28708103, 2017). "The third, genetic alterations such as KRAS mutations can increase the activities of matrix metalloproteases, cysteine proteases, serine proteases, urokinase plasminogen activator, and enzymes responsible for tumor invasion and metastasis." (PMID 28950878, 2017). "Interestingly, four additional KRAS mutations were identified by the ddPCR technique (two tumor specimens, two CTC specimens)." (PMID 28674438, 2017).
tumor (continued). "For patients with a KRAS mutated tumor and patients with a KRAS wild-type tumor, aspirin use after diagnosis was associated with an improved overall survival in the multivariate analysis (KRAS wild-type RR 0.68 (0.67 95%CI 0.47–0.97) and KRAS mutant RR 0.56 (95% CI 0.34–0.93))." (PMID 28125730, 2017). "Notably, the patients were all current or former smokers and in four out of six tumours we identified somatic mutations of KRAS that were frequently associated with the carcinogenic effect of tobacco smoke." (PMID 28194229, 2017). "The IdyllaTM system is a quick, on-demand system that allows fast analysis of hot spot KRAS mutations in exon 2, 3 and 4 starting from 50 mm2 tissue sections with minimum 25% tumor content in order to reach an LOD ranging between 1% ~ 15% depending on the mutation." (PMID 28201998, 2017). "More recent ASCO guidelines have expanded to recommend tumor testing for mutations in KRAS exons 3 (codons 59 and 61) and 4 (codons 117 and 146) as findings from recent Phase II and III trials indicated patients with these mutations also will not benefit from anti-EGFR therapy." (PMID 29202108, 2017). "Once again, all patients had known KRAS mutations in their resected tumor tissue." (PMID 28459822, 2017). "We have recently reported on the use of cell-free DNA (cfDNA) to monitor tumor burden during the treatment of KRAS-mutated adenocarcinoma, a mutation known to be associated with improved outcomes under anti-PD-1 therapy because of its high mutational burden and PD-L1-expression rate." (PMID 28445137, 2017). "Moreover, the pyrosequencing assay employed here is highly sensitive and requires only 10% of tumor DNA in the whole DNA extracted to reliably detect the KRAS mutational status." (PMID 28549417, 2017). "In addition, the expression level of ASCT2 was significantly associated with tumor depth and vascular invasion in KRAS-mutant CRC." (PMID 28749408, 2017). "KRAS gene mutations, which occur in more than 90% of pancreatic intraepithelial neoplasms and carcinomas, are a major cancer initiating event and are required for pancreatic carcinogenesis and tumour progression." (PMID 28701723, 2017). "Concordance between KRAS mutation status in the serum and tumor tissue was 66%." (PMID 29156792, 2017). "The most common mutations of KRAS in the cBioPortal database of tumor tissue are G12C and G12A." (PMID 29290998, 2017). "Similarly, NRP1 can associate with GIPC1 and promote tumor progression through the KRAS/ERK signaling pathway." (PMID 29018205, 2017). "We show that patients with >3 CTC/ml tend to have a worse overall survival (OS) than patients with 0.3–3 CTC/ml and that the KRAS mutations identified in CTCs or primary tumor may differ within the same patient." (PMID 28674438, 2017). "Interestingly, metabolic CRC subtype tumours (CMS3) have been characterized as those which harbor KRAS mutations, a mixed MSI status, low somatic copy number alterations (SCNA), and low CpG island methylator phenotype (CIMP)." (PMID 28956850, 2017). "Thirty‐six EGFR and sixteen KRAS mutations were found in tumor tissues of 168 patients." (PMID 28382702, 2017). "Importantly, we have found here that loss of PDHK4, a key regulator of the pyruvate dehydrogenase complex, caused a profound cell growth inhibition in tumour cells harbouring KRAS mutations." (PMID 28692044, 2017). "However, 3-year DFS was reported separately according to the KRAS mutational status and we used the results from patients with KRAS wild-type tumor in this meta-analysis." (PMID 28415706, 2017). "To elucidate mechanisms underlying STK38L dependency in PDAC cell lines, we characterized the effects of STK38L depletion on expression levels of key proteins in KRAS and general tumor-associated signaling pathways including p21, MYC, MAPK, PI3K, and autophagy." (PMID 29108249, 2017).
tumor (continued). "The authors studied the genotype of 22 genes (Ion Torrent, Ampliseq colon and lung panel), mainly involved in colorectal tumorigenesis, in primary tumor samples and liver metastasis from 7 KRAS-WT patients, both before and after chemotherapy associated to anti-EGFR." (PMID 29221448, 2017). "Since KRAS mutation is among the most common oncogenic mutations associated with tumor growth, we hypothesized that KRAS mutation status may influence the role of NRP1 in tumorigenesis." (PMID 29018205, 2017). "The observed variability in MYC expression levels among tumor cell lines with KRAS mutations prompted us to investigate whether MYC plays a role in anticancer drug resistance." (PMID 28152508, 2017). "The EGFR and KRAS gene mutation can be detected in samples containing as few as 1% tumor cells." (PMID 29290981, 2017). "Furthermore, CMS3 tumours exhibit a prominent metabolic activation with a clear enrichment for multiple metabolism signatures, in connection with the presence of KRAS-activating mutations that have been described as inducing metabolic reprogramming." (PMID 28956850, 2017). "The tumor was also tested for mutations in exons 2, 3, and 4 of the KRAS and NRAS genes, codon 600 of the BRAF gene, and exons 10 and 21 of the PIK3CA gene, and showed a mutation in PIK3CA exon 10, namely the c.1624G>A, p.Glu542Lys (previously reported by our group 15)." (PMID 29072370, 2017). "Since mutations of KRAS occur in more than 90% of tumors, its detection in circulating free tumor DNA (cftDNA) could represent a biomarker to monitor chemotherapy response." (PMID 28801547, 2017). "Genetic characterization, including mutations such as KRAS, may prove useful for prognosis and understanding of tumor biology." (PMID 28674438, 2017). "Deoxyribonucleic acid (DNA) sequencing showed that the tumor harbored KRAS G12A mutation." (PMID 28950878, 2017). "All BRAF and KRAS mutations identified in the exome sequencing data of the polyps were confirmed by targeted molecular analysis which demonstrates the ability of our approach to identify relevant variants with a fraction of variant reads 3 5% in tumour DNA." (PMID 29213343, 2017). "Despite GEO cells harbors a KRAS gene mutation, previous studies from different laboratories including our own, have demonstrated that this cancer cell line is one of the most sensitive to in vitro and in vivo anti-tumor activity of cetuximab treatment." (PMID 28978118, 2017). "KRAS mutation and wild-type hazard ratios for overall survival and progression-free survival were 1.37 (95% CI, 1.08–1.66), 1.46 (95% CI, 1.15-1.77) in blood samples, and 1.16 (95% CI, 1.03–1.28), 1.28 (95% CI, 1.09–1.46) in tumor tissue." (PMID 28415658, 2017). "The NCCN guidelines state that all patients with metastatic CRC should have tumor tissue genotyped for KRAS, NRAS, and BRAF mutations, and patients with any known KRAS or NRAS mutation should not be treated with anti-EGFR therapy such as cetuximab and panitumumab." (PMID 29212173, 2017). "However, before their first dose of panitumumab all 131 patients were tested for tumour mutation status and had tumours with either a confirmed wild-type RAS or KRAS mutation status." (PMID 29183279, 2017). "Thus far, the direct sequencing method has been used as a gold standard method for obtaining information on the KRAS mutation status from the patient's tumor tissues." (PMID 29137388, 2017). "However, there are divergent findings regarding the prognostic value of EGFR and KRAS mutations in circulating tumor DNA (ctDNA)." (PMID 28430611, 2017). "Fifteen KRAS mutations detected in tumor tissues were also found in peripheral blood (15/16, 94%)." (PMID 28382702, 2017). "Mutations in KRAS exon 2 codon 13 are associated with poor prognosis as well as lower survival, whereas mutations in exon 2 codon 12 are associated with more advanced tumours and metastasis." (PMID 28106826, 2017).
tumor (continued). "We observed a perfect match (100% specificity and sensitivity of the BEAMing technique compared to Ion Torrent and Cobas FDA-approved tumor mutation assessment kits) in the results of our analysis of KRAS, NRAS, PIK3CA and BRAF mutations in tumor and prior treatment plasma samples." (PMID 27852040, 2017). "Factors that were associated with statistically significantly worse OS in this analysis included an age of <50 years (p=0.016), right-sided tumor origin (p<0.001), poor differentiation (p<0.001), KRAS mutations (p<0.001), BRAF mutations (p=0.004), and PIK3CA mutations (p=0.007)." (PMID 28424412, 2017). "Targeted resequencing using a smaller ThunderBolts Cancer panel (Raindance Technologies, Billerica, Massachusetts, US) confirmed the identified KRAS mutation in the primary tumour at an allele frequency of 66%, similar to the 60% frequency found using the 900 gene panel." (PMID 28061772, 2017). "Additionally, some other factors, such as different study design (prospective versus retrospective), tumor KRAS/BRAF/PIK3CA mutation status that affected the survival of CRC patients should also be attributed to some of the heterogeneity." (PMID 28977964, 2017). "Whether NSCLC with KRAS mutation have different immunogenicity and hence result in different tumor responses to ICIs is another vital question." (PMID 28525386, 2017). "The fact that different methodologies were used to assess the presence of KRAS mutations in cfDNA (ddPCR) and in the respective tumor tissue (pyro-sequencing) could potentially account for some discordance in our study." (PMID 28328955, 2017). "Conversely, we showed knocking down MTH1 in NSCLC cells with activating KRAS mutations reduces their tumor formation ability and eliminates the highest RAS oncoprotein-expressing subpopulations in the tumor, leading to an overall reduction in ROS levels, as well as Akt signaling." (PMID 28481306, 2017). "All in all, these observations indicate that FOSL1 links KRAS oncogene to genes involved in mitotic fitness, and suggest that AURKA and TACC3 may partially mediate the ‘synthetic sensitivity' of mutant KRAS tumours to FOSL1 loss." (PMID 28220783, 2017). "Moreover, the model predicted higher expression levels of KRAS in the l-OS patient who was found to have a KRAS somatic mutation in her tumor sample." (PMID 29137348, 2017). "In summary, this retrospective study was the first to find that KRAS mutations could play a potential role as a molecular marker for the risk of developing an advanced neoplasia during follow-up." (PMID 28953955, 2017). "In fact, there could thus be more than one KRAS mutation in each PDAC of which one “matches” the tumor: Heterogeneous KRAS mutations within one tumor were found in 7 of 32 tumor samples." (PMID 28674438, 2017). "KRAS mutations were associated with a higher tumor stage (pT) in this study." (PMID 28583095, 2017). "This higher frequency of KRAS mutations that we observed in CTCs may correlate with their aggressiveness and resistance to anti-tumor therapy." (PMID 29100436, 2017). "Finally, we found that there tends to be an association between the presence of KRAS substitutions that are favored within specific tumor types and clinical outcomes." (PMID 26902163, 2016). "However, in our previous study, we have shown that KRAS mutations are indeed observed in microsatellite-unstable tumours and, more importantly, are relatively frequent in tumours exhibiting Type A MSI." (PMID 26298837, 2016). "Interestingly, the G12C mutation (COSM516) was detected in eight of the 12 patients with KRAS mutation in the primary tumor and/or metastasis." (PMID 26968843, 2016).